SYT17 (synaptotagmin 17)
Description:
Plays a role in dendrite formation by melanocytes.
Synonyms: SytXVII; Syt-17
Tractability: Antibody: UniProt places it where antibodies can reach, with medium confidence; its Gene Ontology location is reachable by antibodies, with medium confidence.
Gene: Protein-coding gene on chromosome 16 (19,167,971 to 19,268,332, forward strand). Ensembl gene ENSG00000103528.
Subcellular location: Membrane
Subcellular location (Human Protein Atlas): Cytosol; Nucleoplasm
Gene Ontology:
Molecular function: protein binding; calcium ion sensor activity; calcium-dependent phospholipid binding; SNARE binding
Biological process: positive regulation of dendrite extension; regulation of postsynaptic neurotransmitter receptor internalization; regulation of calcium ion-dependent exocytosis; vesicle-mediated transport
Cellular component: glutamatergic synapse; postsynapse; exocytic vesicle; plasma membrane; membrane
Genetic constraint (gnomAD): Loss-of-function variants: 22 observed, 47.26 expected, observed/expected ratio (o/e) 0.47, 90% interval 0.33 to 0.67. The upper end of that interval is the gene's LOEUF score, 0.67, which puts it in group 2 of 6, group 1 being the genes least tolerant of losing a copy. Missense variants: 519 observed, 640.45 expected, observed/expected ratio (o/e) 0.81, 90% interval 0.75 to 0.87. Synonymous variants: 251 observed, 262.15 expected, observed/expected ratio (o/e) 0.96, 90% interval 0.86 to 1.06.
Homologues: Orthologues: chimpanzee SYT17 (99% identical), rabbit SYT17 (98% identical), guinea pig SYT17 (97% identical), rat Syt17 (96% identical), mouse Syt17 (95% identical), tropical clawed frog syt17 (88% identical), macaque SYT17 (86% identical), pig SYT17 (85% identical), zebrafish syt17 (72% identical). Paralogues in human: SYT3 (31% identical), SYT6 (31% identical), SYT9 (30% identical), SYT10 (30% identical), SYT1 (28% identical), SYT2 (27% identical), SYT7 (27% identical), SYT11 (25% identical), SYT15 (25% identical), SYT15B (25% identical), SYT5 (25% identical), SYT4 (24% identical), and 19 more.
Diseases named in the same sentence as SYT17 in open-access papers:
SYT17 is named in the same sentence as 7 diseases in open-access papers, as found by Europe PMC text mining. Sharing a sentence is not in itself a finding about the gene and the disease. The quoted sentences say what the papers report.
cardiomyopathy (1 paper, 2025). A disease of the heart muscle or myocardium proper. "Repression of Syt17 transcription resolves established cardiomyopathy." (PMID 40279007, 2025).
familial spastic paraplegia (1 paper, 2025). "The plasma membrane Ca2+ exporter encoded by ATP2B4 has been found mutated in familial spastic paraplegia, and voltage-dependent calcium channels comprising the CACNA1E-encoded subunit α1E have been linked to synaptic plasticity, as has been SYT17." (PMID 40019676, 2025).
SYT17 also shares sentences with these, for which no sentence is quoted: Atrophy (1 paper); immune disease (1); Nephropathy (1); non-Hodgkin lymphoma (1); tumor (1).